U2 (U2 spliceosomal RNA )
Synonyms: LOC124904138
Gene: Small nuclear RNA gene on chromosome 17 (43,251,829 to 43,252,019, reverse strand). Ensembl gene ENSG00000278048.
Gene Ontology:
Molecular function: pre-mRNA branch point binding
Biological process: mRNA branch site recognition
Cellular component: U2 snRNP
Homologues: Orthologues: chimpanzee U2 (100% identical), macaque U2 (100% identical), dog U2 (99% identical), pig U2 (48% identical), rat LOC120094029 (36% identical). Paralogues in human: U2 (100% identical), RNU2-2 (96% identical), U2 (95% identical), RNU2-3P (93% identical), RNU2-4P (93% identical), RNU2-17P (90% identical), RNU2-6P (90% identical), RNU2-48P (89% identical), RNU2-52P (89% identical), RNU2-59P (89% identical), RNU2-25P (87% identical), RNU2-26P (87% identical), and 68 more.